JAK3 (Janus kinase 3)
Diseases named in the same sentence as JAK3 in open-access papers (continued):
Sharing a sentence is not in itself a finding about the gene and the disease.
cancer (continued). "Thus, CMTR1 activity seems to be affected in a cancer-associated mutant context and may be one of the downstream explanations for the JAK3 mutant cancer phenotype." (PMID 30764532, 2019). "Besides, quercetin could inhibit the activities of many kinases implicated in cancer cell biology, such as ABL1, Aurora-A, -B, -C, CLK1, FLT3, JAK3, and MET." (PMID 31998395, 2019). "The molecular docking analysis demonstrated that Melittin preferentially binds to key components of the JAK–STAT pathway, particularly JAK2 and JAK3, leading to the suppression of STAT3 activation and disruption of critical cancer-promoting pathways." (PMID 40243485, 2025). "Among others, we found that targeted treatment with JAK3, HER2, or FGFR3 inhibitors showed anti-cancer effects in individual brain metastasis cultures." (PMID 38985431, 2024). "Janus kinases (JaK) are a family of tyrosine kinases (TKs), including JAK1, JAK2, JAK3, and TYK2, and all of their receptors actively participate in the pathogenesis of various human cancers." (PMID 35634509, 2022). "All the other regions were comprised of multiple genes, including a few known cancer genes according to COSMIC Cancer Gene Census v92: SLC34A2 on 4p15.2, RET on 10q11.21, HSP90AA1 on 14q32.31, and JAK3 on 19p13.11." (PMID 35922826, 2022). "All the new compounds were evaluated for their biological properties toward extracellular matrix in rat renal proximal tubular cells, human cancer cells (K562, A549, and Huh7), EV71, ROCK2, JAK3, DDR1, and coagulation." (PMID 32876846, 2021). "Tubulosine potently inhibited constitutively active and IL‐2‐induced JAK3/STAT signalling, thereby decreasing proliferation and survival of cancer cells by inducing apoptotic and necrotic/autophagic cell death." (PMID 32558259, 2020). "ARRB2 and JAK3 were highly expressed in T cells, while PTK2 and ACTG1 were mainly enriched in the 'Cancer cluster." (PMID 32549766, 2020). "To evaluate if IST5 affects kinase activity in cancer cells, we tested kinase inhibitory activity of IST5 in two custom-tailored panels including 54 relevant kinases, including Jak1, Jak2, Jak3, Tyk2, Abl1, Abl2, Lck, Fyn, Src and TrkB/C." (PMID 33217941, 2020). "Current research of JAK3/STAT5 signaling has focused on its role in the immune system and the occurrence and development of various cancers." (PMID 27827939, 2016). "Furthermore, these transcription factors are enriched in cancer-related kinases such as lymphocyte-specific protein tyrosine kinase (LCK), LYN proto-oncogene (LYN), spleen tyrosine kinase (SYK), Janus kinase 3 (JAK3), and FER tyrosine kinase (FER)." (PMID 40612864, 2025). "Current study supports the notion that the discovery of JAK3 and TLR4 antagonists could be an ideal strategy for cancer treatment." (PMID 38149248, 2023). "Therefore, these compounds are predicted to inhibit growth and induce apoptosis of cancer cells through their interactions with MMP12, MMP13, CDK4, JAK3, VEGFR1, VEGFR2, and KCNA3." (PMID 36106139, 2022). "Most recently, Tubulosine from Alangium salvifolium wang has selectively inhibited JAK3 signals by binding to ATP-binding active site of the kinase (JAK3), thereby reducing the progression and survival of hematopoietic cancer, as shown against HDLM-2, L540, U266, and BKO-84 cancer cells." (PMID 36500466, 2022). "As the only non-promiscuous Jak family kinase, targeting Jak3 in the niche has the potential to become a viable means to manipulate hematopoietic output in myriad contexts, from cancer to injury to congenital disease." (PMID 33767339, 2021). "Important genes that impact cancer, such as CD70, JAK3 and GDF15, are found on ch19." (PMID 34063545, 2021). "In addition, mutations of cytokine- and growth factor receptors such as IL7Ra can result in IL-7 receptor hypersensitivity leading to elevated JAK3 activation indicating multilevel control of JAK activation (and deregulation) in cancer." (PMID 33466582, 2021).
cancer (continued). "Collectively, these findings indicate that the inhibitory effect of IST5 on Stat5 phosphorylation in cancer cells is not due to inhibition of Jak2 or other key kinases including Jak1, Jak3, Tyk2, Src, Lck, Fyn, TrkB/C, Abl1 or Abl2." (PMID 33217941, 2020). "Meanwhile, tubulosine did not significantly affect the signalling of other JAK family members and other oncogenic kinases and the survival and proliferation of cancer cells lacking persistently active JAK3." (PMID 32558259, 2020). "In this study, somatic alterations of two cancer-related genes, including the RECQL4 and the JAK3, had significant associations with non-MGC development, and the ARID1A and the MAGI1 genes had significant associations with metachronous development." (PMID 33328548, 2020). "In line with previous observations, genes involved in cancer development were represented on Bs of four studied species: red fox (KIT), Chinese raccoon dog (ENPP1, GNAS, HMGCR, KDR, RET), brocket deer (BCL6, RASA1, RET), and Korean field mouse (JAK3)." (PMID 30103445, 2018). "Beyond JAK3-mediated STAT3 phosphorylation, epigenetic silencing of negative regulators such as PTPN6 may contribute towards sustained STAT3 phosphorylation in cancer cells." (PMID 30420593, 2018). "Cancer cell line HCT116 was treated with trametinib (5μM) alone, or in combination with one of the following agents: ruxolitinib (2.5μM, JAK2 inhibitor), tofacitinib (2.5μM, JAK3 inhibitor) or KX2-391 (2.5μM, Src inhibitor)." (PMID 25961376, 2015). "We detected mutations in several known cancer genes where a link to T-ALL has not been established yet, such as JAK3." (PMID 22675565, 2012). "We further assessed if NSC114792 can specifically inhibit JAK3, but not other JAKs, using various cancer cell lines where constitutively-active JAK kinases are expressed." (PMID 20149240, 2010). "Therefore, we believed that compared to morphine alone, morphine and ketamine can relieve cancer pain of CC patients more effectively via the JAK3/STAT5 pathway without reducing immune function additionally." (PMID 35492074, 2022). "In this study, we investigated the interaction between drug combination and the JAK3/STAT5 pathway in immune functions, and our findings revealed that morphine and ketamine may attenuate cancer pain and suppress immune functions through regulation of the JAK3/STAT5 pathway." (PMID 35492074, 2022). "At present, it remains to be investigated whether nuclear expression of JAK3 involves interaction with POLR2A in healthy, non-malignant T cells or whether this interaction is a unique, cancer-associated feature of malignant T cells." (PMID 33466582, 2021). "Unsurprisingly, CDK inhibitor purvalanol-a, aminopurvalanol-a, JAK3-inhibitor-VI, and topoisomerase inhibitor, cell cycle inhibitor etoposide are top listed compounds (CPs) that showed a strong negative connectivity scores in 8 cancer cell lines." (PMID 33023625, 2020). "An unexpected result of the cancer hotspot panel sequencing approach was the identification of mutations in genes usually associated with non-epithelial malignancies, such as IDH1 R132H/R132C, JAK3 V722I, and FLT3 A680V." (PMID 25656989, 2015). "Interestingly, we also found mutations in several cancer genes that had not been linked to T-ALL before, including JAK3." (PMID 22675565, 2012). "Interestingly, following activity onset (CT38), pathways established to be involved in cancer-induced muscle wasting, including JAK-STAT, tumor necrosis factor (TNF), and FoxO signaling pathways, were enriched from genes increased in KPC mice (e.g., Jak3, Osmr, Nfkbia, Bcl3, Gadd45g, and Cebpb)." (PMID 40349340, 2025). "Consistent with the specificity of NSC114792 for JAK3, it selectively inhibited persistently-activated JAK3, but failed to affect the activity of other JAK family members and other oncogenic kinases in various cancer cell lines." (PMID 20149240, 2010).
infection (20 papers, 2010 to 2025). The state of being infected such as from the introduction of a foreign agent such as serum, vaccine, antigenic substance or organism. "It remains to be seen if the relative difference in inhibition of γc cytokine receptors vs other cytokine receptors (eg, IFN and IL‐6) with tofacitinib, compared with JAK inhibitors that spare JAK3, translates into a meaningful difference in infection risk." (PMID 31832202, 2019). "As the modulation of Jak3 functions is implicated in different therapies, the drugs used to modulate Jak3′s immune functions are associated with severe infection and metabolic dysregulation, and Jak3 inhibition in patients with chronic inflammation also leads to metabolic dysregulation." (PMID 36145091, 2022). "Increased infection risk at higher doses of tofacitinib could also be driven by JAK3 inhibition and subsequent downstream blockade of IL-15 survival signaling in NK cells." (PMID 30886973, 2018). "Inactivation of Jak3 caused a dramatic increase in susceptibility to infection, leading to progressive mortality within 15 days of infection, compared to B6 and Jak3W81R/+ heterozygotes which developed transient disease symptoms but survived the infection." (PMID 22363534, 2012). "The expression of the T cell gene Jak3 was also substantially higher at 60 days post infection in old SDR mice compared to old Home Cage mice, suggesting accumulation of T cells in the lungs of old SDR mice." (PMID 36189368, 2022). "At 30 days post- infection, old Home Cage mice expressed significantly higher levels of JAK3 mRNA compared to young Home Cage mice." (PMID 36189368, 2022). "JAK3 appears to be a specific target since the dephosphorylation continued through day 10 post-infection where an 18-fold decrease was observed." (PMID 27472318, 2016). "There is a gradual reduction of NK cell functional activity from baseline values as a function of time post infection in each of the 16 control monkeys and 15 JAK3 inhibitor group of animals." (PMID 24603870, 2014). "In fact there was a gradual increase in the number of CD8+ T cells that was sustained during the chronic infection period and was significantly (p<0.0001) different from the JAK3 inhibitor group of animals." (PMID 24603870, 2014). "We were expecting that the major effects of the administration of the JAK3 inhibitor during acute infection would be targeting cells involved in mediating innate immune responses such as the NK cell lineage." (PMID 24603870, 2014). "There did not appear to be any statistical difference in the plasma viral loads between the control (Group 1) and the monkeys that received the JAK3 inhibitor (Group 2) during the acute infection period." (PMID 24603870, 2014). "JAK1, JAK2, JAK3, and Tyk2 all became more phosphorylated after infection of ST cells by TGEV." (PMID 28642467, 2017). "However, JAK2 and JAK3 appeared to be targets for dephosphorylation where both had a three-fold decrease in phosphorylation at four days post-infection." (PMID 27472318, 2016). "Thus, how does the administration of a JAK3 inhibitor during “acute” infection lead to such profound effects during “chronic” infection?." (PMID 24603870, 2014). "However, following the acute infection period, there was a gradual increase in the plasma viral loads thereafter that reached statistical significance already during the chronic phase (p<0.0001) in the animals that received the JAK3 inhibitor during acute infection." (PMID 24603870, 2014). "First of all, as early as one week post infection, there was a significant increase in GIT pro-viral DNA load in the JAK3 inhibitor group of monkeys as compared to controls (p<0.0005)." (PMID 24603870, 2014). "Interestingly, the expression of CYBB, JAK3, and GUCY2C was also turned off after vPdR-H30K-5U infection." (PMID 40006915, 2025). "Some other specific proteins such as JAK3 were expressed in IC89 and VN75/1 infections." (PMID 34671358, 2021).
infection (continued). "Importantly, and consistent with the actions of NO and JAK3/STAT1 signals in the modulation of sPLA2 expression, infection of the cells with STAT1 siRNA attenuated LPS-induced permeability mainly through the activation of sPLA2." (PMID 22788969, 2012). "A follow-up study investigated prolonged administration of the JAK3 inhibitor during the acute phase of infection and recapitulated the finding of significant higher virus replication during the chronic phase (>12 weeks) of infection in JAK3-treated MAC, but not during the acute phase of infection." (PMID 31191520, 2019).
hematological malignancies (13 papers, 2012 to 2026). "Because numerous JAK1 and JAK3 variants associated with hematological malignancies are located within dynamic structural loops, it is conceivable that these regions may be more susceptible to allosteric drug-targeting." (PMID 37834019, 2023). "Activating JAK3 mutations are seen in hematological malignancies." (PMID 28359267, 2017). "Aberrant JAK3 activation has been reported in several hematologic malignancies and solid tumors, highlighting its relevance as a potential therapeutic target." (PMID 41385500, 2025). "The JAK family includes JAK1, JAK2, JAK3, and Tyk2, and their inhibition is known to be therapeutic for many autoimmune and hematological diseases." (PMID 39742289, 2024). "JAK mutations have also emerged in other hematologic diseases, and the majority of the pathogenic mutations in JAK2 (also in JAK1 and JAK3) localize in or near the pseudokinase domain." (PMID 26377485, 2016). "FERM domains of JAK1 and JAK3 are identified as a hot spot for hematologic malignancies." (PMID 37834019, 2023).
hematologic cancers (7 papers, 2016 to 2025). "An overlay of full-length human JAK1 and JAK3 shows a clustering of FERM-SH2 domain hematopoietic neoplasm variants along the surface pointing away from the center of the JAK dimer." (PMID 37834019, 2023). "The primary gene alteration here - activation of JAK3 via a recurrent mutation JAK3 (V722I) - was previously reported in a variety of hematopoietic neoplasms as a driver mutation enabling factor-independent growth." (PMID 27144517, 2016). "Despite JAK3 exhibiting great capacity as a druggable target for hematological tumors, the discovery of JAK3 inhibitors remained an enormous challenge." (PMID 37886358, 2023). "Therefore, it was meaningful to discover novel drug-like JAK3 inhibitors with specific sketches and explore their potential usage as therapeutic agents for hematological tumors." (PMID 37886358, 2023). "In addition, other genes known to be affected by somatic mutations in hematologic cancers were also found from the WES data, such as JAK3, CREBBP, BCOR, and so on." (PMID 28410228, 2017).
inflammation (4 papers, 2016 to 2022). Aberrant reaction of the microcirculation characterized by movement of fluid and leukocytes from the blood into extravascular tissues. "On the basis of our results, we conclude that the JAK-STAT pathway is implicated in the progression of renal inflammation in NZB/WF1 mice and that targeting JAK3 with CP-690,550 is effective in slowing down the course of experimental LN." (PMID 27278657, 2016). "That inflammation, immune system activation and imbalance, and cell proliferation and adhesion migration were mainly affected by HLA-DRA, SYK, CTLA4, VAV1, NRAS, and JAK3 signaling pathways was suggested to be the potential molecular mechanism for pulmonary inflammation and fibrosis in ACO." (PMID 33869177, 2021).
adenocarcinoma (3 papers, 2012 to 2025). A common cancer characterized by the presence of malignant glandular cells. "In regards to 11 kinases specifically regulated in AD, siRNA‐mediated gene‐silencing of CDK1, EPHA1, JAK3, RET and ZAP70 caused loss of cell viability in a panel of six human adenocarcinoma cell lines." (PMID 39995112, 2025).
head and neck tumors (1 paper, 2019). "The importance of the signaling way Janus activated kinase-3 (Jak3) in the metastasis of malignant head and neck tumors mediated by CCR7 and its ligands, can be a new target for treatment of these patients." (PMID 31011147, 2019).
renal disease (1 paper, 2016). "To examine the effects of a JAK3 inhibitor on advanced LN in mice, we treated 6-month-old NZB/WF1 female mice with overt renal disease with CP-690,550 and compared this treatment with MMF and CYP as standard therapies." (PMID 27278657, 2016).
JAK3 also shares sentences with these, for which no sentence is quoted: combined immunodeficiency (6 papers); Crohn disease (5); psoriatic arthritis (5); influenza (3); juvenile idiopathic arthritis (3); metabolic disorders (3); skin disorder (3); type 2 diabetes (3); ankylosing spondylitis (2); blood tumors (2); chronic myeloid leukemia (2); chronic obstructive pulmonary disease (2); colonic polyp (2); epidermodysplasia verruciformis (2); fibrosarcoma (2); Insulin resistance (2); lupus nephritis (2); mantle cell lymphoma (2); myeloproliferative diseases (2); pemphigus (2); plaque psoriasis (2); acute promyelocytic leukemia (1); adenosquamous carcinoma (1); AIDS (1); Alopecia universalis (1); Anxiety (1); astrocytoma (1); autoimmune encephalitis (1); avian influenza (1); B-cell neoplasm (1).
A further 79 diseases each share a sentence with JAK3 in 1 paper.